PCSK9 (proprotein convertase subtilisin/kexin type 9)
Diseases named in the same sentence as PCSK9 in open-access papers (continued):
Sharing a sentence is not in itself a finding about the gene and the disease.
liver cirrhosis (11 papers, 2021 to 2025). "Exclusion of patients with liver cirrhosis caused a less significant difference in PCSK9 levels between patients with moderate and severe disease." (PMID 39051245, 2024). "The present evidence indicates that the circulating levels as well as the associations of PCSK9 with the clinical markers of inflammation are affected by liver cirrhosis and SARS-CoV-2 infection." (PMID 37515197, 2023). "Even though these experimental data suggest PCSK9 inhibitors as valuable options in patients with liver cirrhosis, low serum PCSK9 was associated with a higher mortality in patients with end-stage liver disease." (PMID 33461570, 2021). "In the cohort of patients with liver cirrhosis mostly secondary to alcohol consumption high PCSK9 was associated with low levels of certain cholesteryl ester and sphingomyelin species." (PMID 33461570, 2021). "This suggests that associations of PCSK9 and the adipokines chemerin and adiponectin in the hepatic vein possibly reflect the activity of certain pathways which are impaired in liver cirrhosis." (PMID 33461570, 2021). "In fact, in patients with liver cirrhosis, impaired hepatic function seems to override the effect of PCSK9 on cholesterol metabolism, as demonstrated by the loss of the correlation between cholesterol and PCSK9." (PMID 33461570, 2021). "In HCV patients with liver cirrhosis, PCSK9 was low and was associated with markers of liver injury." (PMID 33920491, 2021). "The missing correlation of circulating PCSK9 with cholesterol may be also caused by a high level of inactive PCSK9 in patients with liver cirrhosis, a suggestion which has to be proven in the future." (PMID 33461570, 2021). "Four patients in the moderate and one in the severe group had liver cirrhosis, which was related to reduced PCSK9 in accordance with recent findings." (PMID 39051245, 2024). "The exceptions observed were patients with liver cirrhosis on vasopressor therapy, who had higher plasma PCSK9 levels." (PMID 37515197, 2023). "PCSK9 is highly expressed in the liver and its circulating levels decline in patients with liver cirrhosis." (PMID 37515197, 2023). "A further study also found that serum PCSK9 levels were 20–30% higher in healthy controls compared to patients with chronic hepatitis or liver cirrhosis." (PMID 35162992, 2022). "In patients with liver cirrhosis, serum PCSK9 concentrations were markedly reduced in comparison to healthy controls." (PMID 35162992, 2022). "As compromised liver function in liver cirrhosis has consequences for plasma cholesterol levels, several studies have investigated PCSK9 quantities in end-stage liver disease." (PMID 35162992, 2022). "PCSK9 is highly expressed in the intestine and small intestinal bacterial overgrowth is common in patients with liver cirrhosis." (PMID 33461570, 2021). "At 12 weeks posttreatment, the associations of serum PCSK9 with the MELD score, bilirubin, INR, leukocytes and CRP in the patients with liver cirrhosis persisted." (PMID 33920491, 2021). "Blockage of PCSK9 enhanced LPS clearance and ameliorated systemic and hepatic inflammation in a rat model of liver cirrhosis." (PMID 33461570, 2021). "Systemic inflammation contributes to the progression of liver cirrhosis and LPS increased hepatic PCSK9 expression in mice." (PMID 33461570, 2021). "The underlying pathways and the role of liver cirrhosis on the crosstalk between HCV and PCSK9 levels must be evaluated in detail." (PMID 33920491, 2021). "Furthermore, those who had liver cirrhosis produced significantly lower serum PCSK9 concentrations, and those who had chronic hepatitis or liver cirrhosis showed serum PCSK9 levels that were 20–30% lower than the healthy controls." (PMID 37466835, 2023). "Statin therapy can decrease the incidence of liver cirrhosis, and considering the inconsistent reports currently available, further studies are needed to evaluate whether pharmacological PCSK9 inhibition could be advantageous in this regard." (PMID 35162992, 2022).
liver cirrhosis (continued). "Along these lines, comparable concentrations of PCSK9 in the hepatic and portal vein of patients with liver cirrhosis suggest that the amounts of PCSK9 secreted and cleared by the liver are similar, an observation that has yet to be confirmed in healthy-liver patients." (PMID 35162992, 2022). "There are still concerns about the adverse effects of statins in patients with decompensated liver cirrhosis, and inhibition of PCSK9 may be an alternative approach." (PMID 33920491, 2021). "In this study we hypothesized that systemic PCSK9 levels correlate with cholesterol and / or sphingolipid species and possibly parameters of inflammation in patients with liver cirrhosis." (PMID 33461570, 2021). "Considering the anti-inflammatory and antifibrotic effects of PCSK9 inhibition, blockage of PCSK9 may have multiple beneficial effects in patients with liver cirrhosis." (PMID 33920491, 2021). "PCSK9 was low in patients with liver cirrhosis and correlated with measures of liver injury." (PMID 33920491, 2021). "In patients with liver cirrhosis the present study demonstrated that plasma PCSK9 was neither associated with the severity of liver cirrhosis nor its complications." (PMID 33461570, 2021). "Statins also decrease liver cirrhosis incidence, and further studies must evaluate whether inhibition of PCSK9 is of advantage." (PMID 33920491, 2021). "In patients without liver cirrhosis, a positive association of serum PCSK9 with viral load existed." (PMID 33920491, 2021). "So far it is unclear whether the etiology of liver cirrhosis has an effect on circulating PCSK9." (PMID 33461570, 2021). "In line with this assumption, positive correlations between plasma PCSK9 and the markers of inflammation, namely CRP, leukocyte count, and procalcitonin were only detected in patients with liver cirrhosis." (PMID 37515197, 2023). "In the COVID-19 cohort (without patients with liver cirrhosis), seven patients died, and their PCSK9 levels did not significantly differ from the patients who survived (p = 0.128)." (PMID 37515197, 2023). "Patients with liver cirrhosis under vasopressor therapy had 162.4 (44.7–641.2) ng/mL, while those without had 111.3 (59.0–173.6) ng/mL PCSK9 in plasma, and this difference was determined to be significant." (PMID 37515197, 2023). "Upon viral eradication, neither PCSK9 nor LDL levels in serum changed in cirrhosis patients, identifying an association of liver cirrhosis with reduced serum PCSK9 levels that did not further decline when the virus was eliminated by DAAs." (PMID 35162992, 2022). "The strong decline of serum PCSK9 in cirrhotic patients prompted us to analyze associations of serum PCSK9 and laboratory parameters separately in HCV patients with and without liver cirrhosis." (PMID 33920491, 2021). "Pentraxin 3 is an adequate indicator of inflammation in patients with liver cirrhosis but was not related to PCSK9 levels in any of the blood compartments." (PMID 33461570, 2021). "In liver cirrhosis, plasma PCSK9 was not correlated with Child-Pugh score, Model for End-Stage Liver Disease score, bilirubin or aminotransferases." (PMID 33461570, 2021). "A separate study reported on increased serum PCSK9 values in patients with liver cirrhosis compared to non-cirrhotic patients with chronic liver disease." (PMID 33461570, 2021). "Of note, negative associations of serum PCSK9 with the MELD score, ALT, bilirubin, INR and CRP and positive correlations with albumin and leukocyte count existed in the HCV patients with liver cirrhosis." (PMID 33920491, 2021). "This also applies to patients with liver cirrhosis where PCSK9 was higher in HCV patients than patients with non-viral disease etiology." (PMID 33920491, 2021). "PCSK9 levels did, accordingly, not decline in patients with liver cirrhosis after DAA therapy, which cannot improve liver function within a short time of observation." (PMID 33920491, 2021).
liver cirrhosis (continued). "Serum PCSK9 was low in HCV patients with liver cirrhosis, but patients with HCV-induced liver cirrhosis still exhibited higher serum PCSK9 than patients with non-viral liver cirrhosis." (PMID 33920491, 2021). "A further study could not identify that serum PCSK9 amounts were reduced in patients diagnosed with liver cirrhosis based on noninvasive tests." (PMID 35162992, 2022). "Patients with liver cirrhosis had lower PCSK9 levels than noncirrhosis patients." (PMID 35162992, 2022). "In patients with liver cirrhosis, serum cholesterol and PCSK9 concentrations were not correlated." (PMID 33461570, 2021). "Serum PCSK9 was reduced in patients with liver cirrhosis in comparison to non-cirrhotic patients." (PMID 33461570, 2021). "So far levels of intact and cleaved PCSK9 were not determined in liver cirrhosis patients." (PMID 33461570, 2021). "Therefore, we measured PCSK9 in serum of non-cirrhotic controls and patients with liver cirrhosis." (PMID 33461570, 2021).
Cirrhosis (10 papers, 2015 to 2025). A chronic disorder of the liver in which liver tissue becomes scarred and is partially replaced by regenerative nodules and fibrotic tissue resulting in loss of liver function. "The 20 females without fibrosis, the 27 females with a score of 1, the 7 females with a score of 2, the 1 female with a score of 3, and the 11 females with a score of 4 resembling cirrhosis had similar PCSK9 levels." (PMID 41271978, 2025). "The 10 males without fibrosis, the eight males with a score of 1, the five males with a score of 2, and the four males with a score of 4 resembling cirrhosis had similar PCSK9 levels." (PMID 41271978, 2025). "Nevertheless, serum PCSK9s were found to increase during the liver fibrosisprogress but decrease significantly in the terminal stage of cirrhosis, possiblydue to severely impaired liver function resulting in reduced PCSK9 synthesis." (PMID 39076187, 2022). "The accumulation of ascites is often an early manifestation of acute deterioration of liver function in cirrhosis patients, also termed decompensated cirrhosis, but plasma PCSK9 levels remained unchanged in patients with decompensated disease." (PMID 35162992, 2022). "The three patients with HCV cirrhosis had higher plasma PCSK9 than patients with alcoholic etiology." (PMID 33461570, 2021). "By immunohistochemistry, there was significantly lower expression of PCSK9 in HCC as compared to adjacent cirrhosis (p-value < 0.0001, wilcoxon signed-rank test)." (PMID 26674961, 2015). "Most of the cirrhosis samples, which were obtained just adjacent to the interface between tumor and cirrhotic background, stained strongly for PCSK9." (PMID 26674961, 2015). "Patients with lower PCSK9 levels had a greater frequency of chronic liver disease and cirrhosis." (PMID 35770004, 2022). "Additionally, patients with cirrhosis had higher mean PCSK9 values as compared to chronic liver disease patients without cirrhosis (p-value =0.048)." (PMID 26674961, 2015). "This phenomenon might weaken the efficiency of PCSK9 inhibitors indecompensated cirrhosis patients." (PMID 39076187, 2022). "Interestingly, a negative association of CRP and PCSK9 existed in HCV-infected patients with cirrhosis before therapy and at 12 weeks posttreatment." (PMID 33920491, 2021). "Thus, PCSK9 inhibitors may exert multiple beneficial effects ondecompensated cirrhosis." (PMID 39076187, 2022). "Significantly greater staining of PCSK9 was present in cirrhosis compared to HCC (p value <0.0001), and positivity (percentage of positive cells) was significantly greater in cirrhosis compared to HCC (p-value < 0.0001)." (PMID 26674961, 2015). "HCV infection also elevated serum PCSK9 levels in noncirrhosis and cirrhosis patients as well as HIV-infected patients." (PMID 35162992, 2022). "Negative correlations of serum PCSK9 concentrations and the MELD score were identified in the cirrhosis group." (PMID 35162992, 2022). "Because serum PCSK9 was low in liver cirrhotic patients before therapy start, DAA-treatment-related effects were separately calculated in HCV patients with and without cirrhosis." (PMID 33920491, 2021).
cognitive decline (10 papers, 2019 to 2025). "Since different variables are associated with PCSK9 in a sex-specific way, and sex-differences have been reported in rates and patterns of cognitive decline, we investigated the influence of sex in this relationship." (PMID 33776743, 2021). "Two studies investigated the relationship between AD or cognitive decline and their putative risk associated with PCSK9 inhibitors." (PMID 32606300, 2020). "In conclusion, this study provides compelling evidence that systemic metabolic modulation, particularly lipid-lowering via PCSK9 inhibition, can influence AD-related neuropathology and cognitive decline." (PMID 40948809, 2025). "Preclinical findings consistently showed that elevated PCSK9 may indirectly promote Aβ accumulation, tau hyperphosphorylation, neuroinflammation, and cognitive decline, while genetic deletion or pharmacological inhibition of PCSK9 mitigates these effects." (PMID 41465790, 2025). "In addition, research has indicated that PCSK9 inhibitors improve metabolic dysfunction, brain function impairment, and cognitive decline in insulin-resistant rats." (PMID 39157774, 2024). "Previous studies have indicated that PCSK9 disrupts brain cholesterol homeostasis, cellular apoptosis, BACE1 expression, and Aβ generation, potentially leading to cognitive decline." (PMID 39157774, 2024). "Even though a direct mechanistic link between PCSK9 levels and total Tau and phospho-Tau has not been established, the strong positive correlations that exist between those CSF biomarkers in “at-risk” subjects may indicate a subclinical interaction that might increase the risk of cognitive decline." (PMID 31437157, 2019). "However, these tests were designed to monitor for potential short-term side effects due to PCSK9 inhibition and not for the investigation of cognitive decline progression in a long-term AD therapy." (PMID 35344086, 2022).
dengue (10 papers, 2020 to 2026). "Collectively, these findings indicate that elevated PCSK9 expression is associated with higher viremia and an increased risk of more severe plasma leakage in patients with dengue." (PMID 32644974, 2020). "Given the possibility that PCSK9 inhibitors could be repurposed as anti-dengue therapy, we thus sought to establish an association between plasma PCSK9 levels and disease severity in patients with dengue." (PMID 32644974, 2020). "This unexpected role of PCSK9 in dengue pathogenesis, led us to test the effect of inhibition of PCSK9 function by the mAb Alirocumab." (PMID 34202098, 2021). "This unexpected role of PCSK9 in dengue pathogenesis led us to test the effect of blocking PCSK9 function by the inhibitory PCSK9-mAb alirocumab." (PMID 34606887, 2021). "Our in vitro findings were further supported by the detection of elevated plasma PCSK9 levels in patients with dengue with high viremia and increased severity of plasma leakage." (PMID 32644974, 2020). "These in vitro findings were supported by clinical data that showed a direct correlation between plasma levels of PCSK9 with higher viremia levels and disease severity in patients with dengue." (PMID 32644974, 2020). "Although we have used alirocumab to demonstrate a functional role for PCSK9 in DENV infection, our findings suggest an anti-dengue potential for anti-PCSK9 inhibitors." (PMID 32644974, 2020). "PCSK9 inhibitors can increase antiviral interferon levels, thereby benefiting dengue patients." (PMID 38940622, 2024). "Dengue virus infection induced the expression of proprotein convertase subtilisin/kexin type 9 (PCSK9), which decreases the recycling of low-density lipoprotein receptor to promote cholesterol redistribution into ER repressing ER-resident STING and type I interferon activation." (PMID 36799796, 2023). "It has been shown earlier that in Dengue virus infection, a PCSK9 inhibitor could interfere with the production of IL-6, thereby reducing the inflammatory response." (PMID 37068045, 2023). "Other studies have indicated that PCSK9 inhibits IFNB1 expression, and contributes to dampened antiviral cellular responses in Dengue fever patients, which could be abrogated by a PCSK9 inhibitor." (PMID 35224060, 2022). "Our data suggested that PCSK9 inhibitors could be a suitable host-directed treatment for patients with dengue, possibly in combination with Furin(-like) inhibitors." (PMID 34202098, 2021). "Repurposing PCSK9 inhibitors, either on their own or in conjunction with statins, could thus be an expedient approach to fill the therapeutic void for dengue treatment." (PMID 32644974, 2020). "Plasma PCSK9 concentrations increase in patients with severe dengue." (PMID 32644974, 2020). "Our findings therefore suggest that PCSK9 plays a hitherto unrecognized role in dengue pathogenesis and that PCSK9 inhibitors could be a suitable host-directed treatment for patients with dengue." (PMID 32644974, 2020). "However, the mean levels of PCSK9 in patients with grade 0, 1, or 2 dengue on illness days 4–6 after illness onset were 46.11 ng/mL, 95.76 ng/mL, and 145.8 ng/mL, respectively, indicating elevated PCSK9 levels in patients with more severe disease." (PMID 32644974, 2020). "That PCSK9 plays an important role in DENV infection under such low-oxygen conditions could thus not have been gleaned from conventional experimental studies on dengue that incubate virus and cells at ambient O2 levels." (PMID 32644974, 2020). "Importantly, our study suggests that inhibition of PCSK9 activity using an inhibitory mAb or RNA interference approaches could be safe therapeutic strategies for the treatment of patients with dengue." (PMID 32644974, 2020). "Our PCSK9 finding also suggests that reduced plasma LDL-C levels in patients with severe dengue were not due to increased LDL-C uptake." (PMID 32644974, 2020). "PCSK9 would thus not have a significant impact on dengue pathogenesis in a mouse model." (PMID 32644974, 2020).
Hyperinsulinemia (10 papers, 2015 to 2023). An increased concentration of insulin in the blood. "Many comorbidities (kidney insufficiency, hypothyreoidism, hyperinsulinemia, inflammation) modify PCSK9 expression and release." (PMID 28176216, 2017). "Indeed, in HepG2 cells, hyperinsulinemia decreases PCSK9 expression, an effect which is also observed in post-menopausal obese women." (PMID 25600226, 2015). "On the contrary, in healthy men 24 h hyperinsulinemia did not alter plasma PCSK9 concentrations and PCSK9 expression is similar in normal, pre- and Typ2-diabetic patients." (PMID 25600226, 2015).